PCNA (proliferating cell nuclear antigen)
Diseases named in the same sentence as PCNA in open-access papers (continued):
Sharing a sentence is not in itself a finding about the gene and the disease.
liver cirrhosis (8 papers, 2007 to 2025). "Accordingly, increased levels of Ki67 and PCNA, as well as more HepG2 cells, were observed in the background of liver cirrhosis, revealing increased proliferation ability in a stiffer environment." (PMID 41387479, 2025). "Contrary to this, TAA control rats showed an increased presence of PCNA stains and an up-regulated mitotic index as signs of tissue proliferation and liver cirrhosis induced by TAA." (PMID 37662795, 2023). "The extract from G. mangostana effectively protects against thioacetamide (TAA)-induced liver cirrhosis by significantly reducing the expression of hepatic proliferating cell nuclear antigen (PCNA), TGF-β1, and α-SMA." (PMID 38034260, 2023). "Liver cirrhosis showed upregulation of PCNA, indicating extensive proliferation for the replacement of the damaged tissues." (PMID 24396831, 2013). "Similarly, exposure that green tea potentially inhibited the progression of liver cirrhosis, and down-regulation of PCNA proliferation." (PMID 36458098, 2023). "Moreover, enhanced expression of NPM in HCC correlated with the level of PCNA (R2=0.5639) and with the clinical prognostic parameters such as serum alpha fetal protein level, tumour pathological grading, and liver cirrhosis (P<0.05)." (PMID 17245342, 2007). "Notably, proliferating cell nuclear antigen (PCNA), which is the basic element in DNA replication and repair, was significantly increased in the medium and the high dose Exo-rBMMSC groups compared to the liver cirrhosis group (*** p < 0.001)." (PMID 36552767, 2022). "The immunohistochemical outcomes have shown that TAA controls experienced severe liver cirrhosis, fibrosis, and cellular proliferation, as shown by increased concentrations of α-SMA and PCNA proteins in their liver tissue." (PMID 37662795, 2023).
odontogenic cyst (8 papers, 2012 to 2024). A cyst in the jaw that arises from tissues of tooth development.
polymyositis (8 papers, 2018 to 2025). A rare idiopathic inflammatory myopathy characterized by symmetric proximal muscle weakness and elevated muscle enzymes. "These included – Polymyositis/Scleroderma antigen 100 (Pm/Scl-100), Proliferating Cell Nuclear Antigen (PCNA), Anti-liver cytosolic antigen type 1 (LC-1), and Heterodimer Ku protein subunits 70 & 80 (KU P70/P80)." (PMID 39936155, 2024).
prostate tumor (8 papers, 2013 to 2025). "Recently, it was also demonstrated that lycopene and beta-carotene impair the growth of prostate tumor cells, which was associated with a decrease in proliferating cell nuclear antigen expression and with the insulin-like growth factor I signaling pathway." (PMID 23667519, 2013). "Proliferation markers (MKI67 and PCNA) were highly expressed in prostate tumor tissue of Pten/Smad4 KO mice but barely detected in prostate tissue of Pten/Smad4/Kmt9α KO and Ctrl mice." (PMID 39885202, 2025). "Melatonin, the darkness hormone, has been reported to be an antiproliferative agent that decreases PCNA expression in a hormone-dependent manner in vivo and in vitro in mice prostate tumors and in female rat ovarian cells." (PMID 33204259, 2020). "We observed similar staining pattern with Ki67 and PCNA in consecutive serial sections of inflamed tonsil and confirmed that in certain areas of the prostate tumor there was a permissive microenvironment, which supported immune cell proliferation." (PMID 28567040, 2017). "However, neither APE2 nor PCNA expression values was significantly different in matched prostate tumor, thus there is no baseline to strengthen the implications of this APE2-PCNA correlation." (PMID 32111912, 2020).
Sepsis (8 papers, 2013 to 2025). Sepsis is defined as life-threatening organ dysfunction caused by a dysregulated host response to infection. "Animals with severe sepsis displayed lower PCNA levels and higher mortality compared with those having a moderate phenotype." (PMID 35814769, 2022). "Menthol administration significantly (p < 0.05) attenuated the sepsis-induced decline in PCNA expression." (PMID 36120368, 2022). "Experimental induction of severe sepsis reduced the expression of PCNA, which correlated with diminished hepatic tissue regenerative capacity." (PMID 35814769, 2022). "We introduced a role of the proliferating cell nuclear antigen (PCNA) in these tissues with a possible link to the damage induced by sepsis." (PMID 35814769, 2022). "In sepsis, increased hepatic inflammation and apoptosis decrease the gene expressions of PCNA, as shown in this study and other studies." (PMID 36120368, 2022). "Consistent with our findings, experimental induction of sepsis reduced the expression of PCNA in hepatocytes, and cardiomyocytes." (PMID 35814769, 2022). "Hepatic levels of PCNA, an index of cell proliferation and regeneration, were significantly (p < 0.05) decreased in the sepsis group." (PMID 36120368, 2022). "The expression of PCNA in the intestine was significantly decreased after sepsis, indicating that the proliferation ability was significantly decreased." (PMID 34039427, 2021). "qPCR analysis showed that two reliable markers of cell proliferation, MAPK1 and PCNA, were up-regulated by sepsis and decreased by compstatin treatment both at T0 and T+5." (PMID 26337158, 2015). "Additionally, menthol enhances biomarkers associated with regeneration and survival, such as B-cell lymphoma 2 (an anti-apoptotic factor) and proliferating cell nuclear antigen, following sepsis-induced liver injury." (PMID 40333131, 2025). "However, whether this preservation of PCNA level is a consequence of the menthol-induced reduction of sepsis severity via reducing oxidative stress and inflammation or is a direct effect of menthol is yet to be answered." (PMID 35814769, 2022). "The nuclear proteins proliferating cell nuclear antigen (PCNA) and myeloid nuclear differentiation antigen (MNDA) play opposing roles in modulating neutrophil apoptosis in patient with sepsis." (PMID 23986764, 2013).
squamous cell carcinoma (8 papers, 2012 to 2025). A carcinoma arising from squamous epithelial cells. "In their study, the PCNA was increased 4-10-fold from adjacent normal epithelium to squamous cell carcinoma." (PMID 37809121, 2023). "Significantly elevated levels of Ki-67, p27, and PCNA in IP with squamous cell carcinoma transformation of sinonasal tract compared with inverted papilloma were revealed." (PMID 25013792, 2014). "Higher expression of PCNA was found in poorly differentiated squamous cell carcinoma." (PMID 37809121, 2023). "In a molecular study by Proliferating cell nuclear antigen (PCNA) on potentially malignant disorders and squamous cell carcinoma, it was confirmed that higher the cell proliferation rate, the higher the risk of cells suffering mutations during mitosis, which could result in malignant phenotype." (PMID 22549675, 2012). "Tumors developed under the effects of prenatal exposure contained basal cell carcinoma (BCC) and squamous cell carcinoma (SCC) types, with increased levels of PCNA, MMP 9, and Vimentin at 18 weeks." (PMID 38519574, 2024). "In this study, we evaluated the immunohistochemical expression of PCNA and CD57 in 10 cases each of well-differentiated, moderately differentiated, and poorly differentiated squamous cell carcinomas." (PMID 37809121, 2023). "Moreover, ILF3 overexpression in adenocarcinoma, and PCNA and NEDD8 in squamous carcinoma shows them as promising candidates for therapeutic purposes." (PMID 27814385, 2016). "We also found the elevated PCNA, Ki-67, and p27 in the sinonasal IPs with squamous cell carcinoma transformation compared with sinonasal IPs alone with no synchronous malignancy." (PMID 25013792, 2014).
ulcer (8 papers, 2010 to 2025). "FGF-1 can significantly increase the number of capillaries and fibroblasts in ulcer tissue, and enhance the expression of transforming growth factor-β and nuclear antigen proliferating protein (PCNA), thus improving diabetic ulcer tissue." (PMID 34721299, 2021). "The mean area percent of PCNA immunostaining positive cells was significantly decreased in ulcer compared with control." (PMID 34829707, 2021). "CQE increased the number of PCNA labeled cells at the ulcer margin on day 7 after ulcer induction when compared with the respective ulcerated group." (PMID 20931084, 2010). "In addition to determining how well EGb 761 works to prevent and treat indomethacin-induced stomach ulcers in mice, this study sought to clarify the impact of oxidative, nitrosative, and inflammatory biomolecules, as well as COX-2 and PCNA, in the development and progression of ulcers." (PMID 36080365, 2022). "EGb 761 treatments, both prophylactic and therapeutic, resulted in significant reductions in ulcer lesions, nitrosative and oxidative damage, and inflammatory markers, along with the lowering of COX-2 and PCNA expressions." (PMID 36080365, 2022). "The administration of the extract in the two models tested increased the PAS (Periodic Acid of Schiff’s method) staining of mucin, reduced myeloperoxidase activity at the ulcer site, and improved the immunostaining of PCNA (proliferating cell nuclear antigen)." (PMID 36518668, 2022). "More so than in the pre-treated animals, the EGb 761-treated groups showed improved score, levels, and expressions of the ulcer index, MDA, GSH, NO, IL-6, TNF-α, IL-1β, COX-2, and PCNA." (PMID 36080365, 2022). "It has been found that aFGF significantly increases the number of capillaries and fibroblasts in ulcer tissue, and enhances the expression of TGF-í and PCNA proliferative proteins, thus promoting the healing of diabetic ulcer." (PMID 34721299, 2021). "In contrast, the ethanol-induced ulcer exhibited negative immunoreaction while in pretreated rats exhibited weak to moderate positive immunoreaction of PCNA, while in treated rats were showed moderate to strong positive immunoreactions of PCNA." (PMID 34829707, 2021).
acute myeloid leukemia (7 papers, 2003 to 2024). Acute myeloid leukemia (AML) is a group of neoplasms arising from precursor cells committed to the myeloid cell-line differentiation. "Further, cytoplasmic PCNA connects glycolysis and cell survival in acute myeloid leukemia, echoing the significance of the interaction of cytoplasmic PCNA with components of glycolysis and cancer." (PMID 32597793, 2020). "We next investigate PCNA localization in blasts from patients with acute myeloid leukemia (AML)." (PMID 27759041, 2016). "Furthermore, this functional activity of cytoplasmic PCNA was also demonstrated in patients with acute myeloid leukemia (AML)." (PMID 27759041, 2016). "Bone marrow and peripheral blood samples from 362 patients with acute lymphoblastic leukaemia (ALL) proliferating cell and 90 patients with acute myeloid leukaemia (AML) were analysed for S-phase fractions, Ki67 antigen, and proliferating cell nuclear antigen expression." (PMID 12618889, 2003).
esophageal cancer (7 papers, 1999 to 2025). A primary or metastatic malignant neoplasm involving the esophagus. "Here, we combine them and propose that the co-expression of CHAF1A and PCNA is a prognostic biomarker for esophageal cancer." (PMID 37189802, 2023). "Related studies have shown that TDH can inhibit the proliferation of esophageal cancer cells by regulating the cell cycle and reducing proliferating cell nuclear antigen expression." (PMID 32454851, 2020). "In addition, correlation analysis of gene expression using TCGA data revealed a significant positive association between QSOX2 and the cell proliferation markers MKI67 and PCNA in the esophageal carcinoma (ESCA) cohort." (PMID 40433832, 2025). "Increased PCNA expression is observed in a variety of tumors including esophageal carcinoma." (PMID 30940778, 2019). "However, in oesophageal cancer, many indicators of poor prognosis, such as Ki-67 and PCNA, which are cell proliferation markers, are expressed at the invasive front of the tumour." (PMID 18841153, 2008). "Therefore, the downregulation of this hnRNP A2/B1 by resveratrol in the present study in the three esophageal cell systems could have a profound effect on curbing the growth potential of esophageal cancers, because pivotal entities such as PCNA and Ki 67 are shown to be downregulated by this entity." (PMID 34830970, 2021). "In addition, protein expression of proliferating cell nuclear antigen (PCNA), matrix metalloproteinase (MMP-2), and E-cadherin in esophageal cancer cells was determined by Western blot analysis." (PMID 30940778, 2019). "The PCNA LI was independent of known prognostic factors on local control for oesophageal cancer, although Ki-67 LI correlated with several prognostic factors." (PMID 10408843, 1999). "Western blotting of 17 esophageal cancer cell lines showed that the expression of CHAF1A and PCNA were not completely consistent." (PMID 37189802, 2023).
oral squamous cell carcinoma (7 papers, 2019 to 2024). "Further, elevated levels of PCNA and cyclin-D1 have been associated with more aggressive behavior in oral squamous cell carcinoma (OSCC), leading to multidrug resistance and exerting a detrimental effect on the prognosis and overall outcome of patients." (PMID 39124760, 2024). "Inhibiting HDAC1 with PCI-24781 or siRNA reduced oral squamous cell carcinoma (OSCC) cell proliferation by affecting proliferating cell nuclear antigen (PCNA) regulation and mRNA stability." (PMID 38702756, 2024). "Oral squamous cell carcinomas with higher PCNA expression had significantly shorter 5-year overall survival than those with lower PCNA expression." (PMID 37809121, 2023). "The mean value of the PCNA labeling index was 26.19 ± 1.25, 45.88 ± 2.20, 59.38 ± 1.04, and 72.77 ± 4.35 in normal mucosa, well-differentiated OSCC, moderately differentiated OSCC, and poorly differentiated oral squamous cell carcinoma (OSCC) respectively." (PMID 37809121, 2023).
renal carcinoma (7 papers, 2014 to 2025). A carcinoma arising from the epithelium of the renal parenchyma or the renal pelvis. "Immune expression of the cell proliferation marker PCNA and caspase-3 showed that the renal cancer group had significantly higher expression of PCNA and significantly lower expression of caspase-3." (PMID 41068541, 2025). "In rats, hesperidin also inhibits renal cancer progression by inhibiting inflammatory pathways and decreasing PCNA expression." (PMID 36139707, 2022). "Our previous study also demonstrated that DACH1 inhibited cyclin D1 expression and inversely correlated with PCNA in renal cancer cells or blocked cell proliferation through a c-Jun DNA-binding partner." (PMID 27888806, 2016). "Importantly, co-expression analysis demonstrated reverse relationship between protein expression of DACH1 and PCNA in renal cancer tissues." (PMID 25322986, 2014). "The mRNA profiles GSE14994 consisting of 70 patients with renal cancers showed that DACH1 and PCNA were inversely correlated (p < 0.002)." (PMID 25322986, 2014).
Insulin resistance (6 papers, 2011 to 2025). Increased resistance towards insulin, that is, diminished effectiveness of insulin in reducing blood glucose levels. "The endothelial dysfunction in the insulin resistance state is exacerbated by a decrease in blood and oxygen supply, leading to a defense mechanism overexpression of endothelial cell PCNA, which was prominent in the current study." (PMID 39610878, 2024). "The diabetic control group exhibited pancreatic dysfunction as evidenced by the reduction in serum insulin, homeostasis model assessment of ß-cell function (HOMA-β), expressions of PI3K/AKT, Bcl-2, and PCNA combined with an elevation in homeostatic model assessment of insulin resistance (HOMA-IR)." (PMID 35308202, 2022).
keloid (6 papers, 2013 to 2025). An irregularly shaped, elevated mark on the skin caused by deposits of excessive amounts of collagen during wound healing. "This region also showed strong positivity with Hsp70, TGF-β, and PCNA staining, and it was even stronger than keloid center." (PMID 24260741, 2013). "Compared to normal dermis, markedly increased immunopositivity for PCNA was noted in central keloid region and also in extended region." (PMID 24260741, 2013). "Using PCNA staining, we showed increased proliferative activity of keloid fibroblasts than adjacent normal fibroblasts." (PMID 24260741, 2013). "Therefore, PCNA was also detected to verify the influence of H2S on keloid fibroblast proliferation." (PMID 35774378, 2022). "Immunohistochemistry staining of the cell proliferation markers proliferating cell nuclear antigen and Ki-67 showed significantly higher expression levels in keloid dermis than those in normal dermis, suggesting increased proliferation of dermal cells in keloid tissues." (PMID 27897224, 2016). "Also, immunohistochemistry and western blot analysis revealed increased Hsp70, TGF-β, and PCNA expressions in keloids compared to normal tissue." (PMID 24260741, 2013). "Our present study found that NaHS pretreatment slowed down keloid fibroblast migration, decreased the expression of α-SMA, PCNA, collagen I, and collagen III." (PMID 35774378, 2022). "Similar to the preventive effects against keloid fibroblasts, NaHS pretreatment also inhibited cell migration and suppressed the expression of α-SMA, PCNA, collagen I, and collagen III in TGF-β1-stimulated skin fibroblasts." (PMID 35774378, 2022).
mesothelioma (6 papers, 2014 to 2025). A usually malignant and aggressive neoplasm of the mesothelium which is often associated with exposure to asbestos. "There are also several similarities with mesothelioma in this respect where overexpression of two or more of CDK7, GTF2H2, PCNA, RFC4, and the RFC5 were shared by the lung tumors." (PMID 25325012, 2014). "Furthermore, lower expression of CDK7, AKT1, PARP1 (p < 0.1), CCND2 (cyclin D2), CDK2, CDK4, BIRC5 (survivin), PCNA and CDH2 (N-cadherin) (p < 0.005) have been shown to result in longer median survival of patients with mesothelioma." (PMID 36304150, 2022).